ENOX2 (ecto-NOX disulfide-thiol exchanger 2)
Diseases named in the same sentence as ENOX2 in open-access papers (continued):
Sharing a sentence is not in itself a finding about the gene and the disease.
cancer (continued). "The predictive correlation between ONCOblot findings and actual onset of cancer is based on observations that a positive ONCOblot indicates the presence of ENOX2 which is a definitive marker of cancer presence." (PMID 24393573, 2014). "Sera from individual patients with various forms of cancer were analyzed by 2-D gel electrophoresis and immunoblotting to assign each of the ENOX2 isoforms to a cancer of a particular tissue of origin." (PMID 24393573, 2014). "The ENOX2 protein has an influence on the invasion of immune cells into cancer tissue." (PMID 39519404, 2024). "This is particularly interesting in combination with immune checkpoint inhibitor therapy, as the effects of this therapy could be enhanced by inhibiting the increased ENOX2 expression in cancer tissue." (PMID 39519404, 2024). "Unlike most published cancer markers, cancer-specific ENOX2 variants are not simply present as elevated levels of a serum constituent present in lesser amounts in the absence of cancer." (PMID 24393573, 2014). "Generic ENOX2 is frequently associated with early stage cancer, is not organ site specific and exhibits a uniform molecular weight of 34 ± 1 kDa (isoelectric point, pH 3.8 ± 0.1) which is always less than that of the organ site specific transcript variants." (PMID 24393573, 2014). "Neither the splice variant mRNAs nor the ENOX2 isoform proteins are present in detectable levels in non-cancer cells or in sera of subjects without cancer." (PMID 24393573, 2014). "Of the 110 subjects, 66 were negative in the ONCOblot® Tissue of Origin Cancer Test, indicative of the absence of ENOX2 transcript variants or a level of ENOX2 transcript variants below the level of detection in the test." (PMID 24393573, 2014). "ENOX2 is a cancer biomarker of high clinical importance for its potential in both diagnostics and therapeutic targeting, but efficient and sensitive clinical tools for ENOX2 detection are currently limited, requiring off-site testing and dedicated lab environments." (PMID 37504074, 2023). "For example, CETSA was used to show that capsaicin inhibits the G1 cyclin/CDK complex via direct binding to tNOX (ENOX2), resulting in G1 arrest in cancer cells." (PMID 40362180, 2025). "Therefore, the present study was to determine whether an oral decaffeinated green tea product might be effective in early cancer intervention with efficacy based on elimination or reduction to below the limits of detection of the cancer-specific ENOX2 proteins from subjects’ sera." (PMID 24393573, 2014). "Some authors assume that the occurrence of ENOX2 protein is limited to malignant tumors, as ENOX2, according to them, does not occur in the serum of healthy subjects and patients with other diseases." (PMID 39519404, 2024). "tNOX is a growth-related tumor-associated NADH (or hydroquinone) oxidase (ENOX2) that catalyzes the generation of NAD+ and is expressed in cancer cells but not in non-transformed cells." (PMID 36230644, 2022). "Accumulating evidence indicates that capsaicin preferentially inhibits a tumor-associated NADH oxidase (tNOX, ENOX2) that is ubiquitously expressed in cancer but not in non-transformed cells." (PMID 31635402, 2019). "The antibody cross-reacted with all known ENOX2 forms from hematological and solid tumors of human origin but, of itself, did not differentiate among different kinds of cancers." (PMID 24393573, 2014). "Tea catechins, especially EGCg, in combination with Capsicum have been characterized as specific ENOX2 inhibitors inducing apoptotic cell death in cancer but not in non-cancer cell lines." (PMID 24393573, 2014).
tumor (21 papers, 2005 to 2026). "We further addressed the cellular outcome of SIRT1 inhibition by these compounds and found that, in addition to SIRT1, the water-soluble 4-dmH preferentially targeted a tumor-associated NADH oxidase (tNOX, ENOX2)." (PMID 38567911, 2024). "High ENOX2 expression leads to an induction of epithelial–mesenchymal transition, which causes an increase in the invasiveness and migration of tumor cells." (PMID 39519404, 2024). "The effects of ENOX2 on proliferation and invasiveness also explain the association of ENOX2 expression with tumor thickness, tumor stage and sample entity observed in the tissue microarray." (PMID 39519404, 2024). "The interaction between compounds and tumor-associated NADH oxidase (tNOX, ENOX2) was studied by cellular thermal shift assay (CETSA)." (PMID 30909652, 2019). "Considering this, immunohistochemical ENOX2 intensity cannot serve as an independent biomarker, as its function influences other prognostic parameters such as tumor thickness and stage." (PMID 39519404, 2024). "We report that in addition to targeting SIRT1, as does its parental heliomycin, 4-dmH engages with the tumor-associated NADH oxidase (tNOX, ENOX2), as analyzed by CETSAs and molecular docking studies." (PMID 38567911, 2024). "Nevertheless, the immunosuppressive S1P production would be restricted in the tumor microenvironment and the proliferation of tumor cells would be reduced by the direct effects of ENOX2 inhibition." (PMID 39519404, 2024). "The discrepancy in their ability to reduce NAD+ generation led us to explore the role of a tumor-associated NADH oxidase (tNOX, ENOX2) in 4-dmH-suppressed SIRT1 and apoptosis induction." (PMID 38567911, 2024). "Our data confirm this association between ENOX2 expression and immune infiltration, as the proportion of high ENOX2 expression was significantly higher in tumor samples with few eTILs (≤16.6%)." (PMID 39519404, 2024). "This leaves ER and ENOX2/PMET as well described potential molecular targets mediating cellular effects of idronoxil in tumor and normal cells." (PMID 36936272, 2022). "Biological studies revealed that these derivatives exert cytotoxicity via multiple mechanisms, such as by down-regulating a tumor-associated NADH oxidase (tNOX, ENOX2) and Sirtuin 1 (SIRT1)." (PMID 30909652, 2019). "The expression of ENOX2 was significantly different within the categories of sample entity (p = 0.024), stage of PM (p < 0.001), tumor thickness of PM (p < 0.001) and electronic tumor-infiltrating lymphocytes (eTILs; p = 0.031)." (PMID 39519404, 2024). "Based on these data, a tumor-specific occurrence of the ENOX2 protein does not appear to be the case." (PMID 39519404, 2024).
head and neck tumor (1 paper, 2026). "Complementary analyses of public transcriptomic and proteomic datasets revealed elevated ENOX2 expression in human head and neck tumor tissues compared with adjacent normal tissues." (PMID 41596158, 2026).
ENOX2 also shares sentences with these, for which no sentence is quoted: colon cancer (5 papers); bladder cancer (4); gastric cancer (3); stomach cancer (3); breast carcinoma (2); glioblastoma (2); adenocarcinoma (1); colorectal tumor (1); head-neck cancer (1); Hepatic fibrosis (1); hepatocellular carcinoma (1); infection (1); liver cancer (1); lymphoma (1); ovarian carcinoma (1); pleural plaques (1); small cell lung carcinoma (1); stomach adenocarcinoma (1).